TPM3P9 (tropomyosin 3 pseudogene 9)
Gene: Transcribed processed pseudogene on chromosome 19 (53,441,863 to 53,442,607, forward strand). Ensembl gene ENSG00000241015.
Diseases named in the same sentence as TPM3P9 in open-access papers:
TPM3P9 is named in the same sentence as 8 diseases in open-access papers, as found by Europe PMC text mining. Sharing a sentence is not in itself a finding about the gene and the disease. The quoted sentences say what the papers report.
clear cell renal cell carcinoma (2 papers, 2025). "Here, we show that the novel protein TPM3P9, encoded by the lncRNA tropomyosin 3 pseudogene 9, exhibits oncogenic activity in clear cell renal cell carcinoma (ccRCC) by enhancing oncogenic RNA splicing." (PMID 39865075, 2025). "Recent studies reported that the micropeptide TPM3P9, encoded by lncRNA TPM3P9, has oncogenic activity in clear cell renal cell carcinoma (ccRCC)." (PMID 41181701, 2025). "Further investigations demonstrated the clinical significance and biological function of TPM3P9 in clear cell renal cell carcinoma (ccRCC), revealing that TPM3P9 promotes tumor growth by enhancing the alternative splicing of oncogenic RNAs." (PMID 39865075, 2025).
liver cancer (1 paper, 2025). An epithelial or non-epithelial malignant neoplasm that arises from the liver. "Specifically, TPM3P9 expression is higher in kidney, breast, colon, head and neck, uterine, and liver cancers compared to the corresponding adjacent normal tissues, whereas TPM3P9 expression in lung cancer tissues was lower than that in non-cancerous tissue." (PMID 39865075, 2025).
renal carcinoma (1 paper, 2025). A carcinoma arising from the epithelium of the renal parenchyma or the renal pelvis. "Aberrantly high expression of TPM3P9 was associated with poor prognosis in renal cancer patients." (PMID 39865075, 2025). "Collectively, our findings functionally and clinically characterize the “noncoding RNA”-derived microprotein TPM3P9 and thus identify potential prognostic and therapeutic factors in renal cancer." (PMID 39865075, 2025). "Western blot analysis confirmed that overexpression of the TPM3P9 protein in renal cancer cells upregulated RELB expression." (PMID 39865075, 2025).
renal cell carcinoma (1 paper, 2025). "TPM3P9 represents the product of one of our ongoing efforts to identify new microproteins in ccRCC, which accounts for 70%-80% of renal cell carcinomas." (PMID 39865075, 2025).
cancer (2 papers, 2024 to 2025). A tumor composed of atypical neoplastic, often pleomorphic cells that invade other tissues. "In the present study, we conducted a large-scale screening of lncRNA-encoded proteins (LEPs) in pan-cancer through a combination of translatomics and proteomics analysis and identified a lncRNA-derived microprotein, TPM3P9, which exhibits widespread expression across human cancers." (PMID 39865075, 2025). "From a clinical perspective, TPM3P9 expression is upregulated in cancer tissues and is significantly correlated with the expression of TCF7L2-L and RELB." (PMID 39865075, 2025). "In the SYSUCC cohort, TPM3P9 was ubiquitously expressed across nearly all types of cancer." (PMID 39865075, 2025). "Moreover, from the standpoint of the downregulated ncRNAs, the functional role of the TPM3P9 pseudogene in cancer remains unexplored." (PMID 39456519, 2024).
tumor (1 paper, 2025). "Collectively, these data suggest that TPM3P9 exerts its pro-tumor effect by modulating RBM4-mediated RNA splicing." (PMID 39865075, 2025). "Conversely, the ability of TPM3P9 to promote ccRCC cell proliferation and tumor growth was markedly suppressed by overexpression of RBM4." (PMID 39865075, 2025). "Analysis of TCGA and CPTAC data showed that both the mRNA and protein expression levels of TPM3P9 were higher in ccRCC tissues than in the corresponding adjacent non-tumor tissues." (PMID 39865075, 2025). "Our in vitro and in vivo experiments demonstrated that overexpression of TPM3P9 in ccRCC cells increased cell viability and promoted tumor growth." (PMID 39865075, 2025). "Furthermore, results from the xenograft model demonstrated that TCF7L2-L overexpression increased xenograft growth and was able to abolish the suppression of tumor growth resulting from TPM3P9 knockout." (PMID 39865075, 2025). "In vivo models were used to examine the impact of TPM3P9 depletion on tumor growth." (PMID 39865075, 2025). "Overexpression of TPM3P9 promotes cell proliferation and tumor growth." (PMID 39865075, 2025). "Tumor growth was significantly inhibited by knockout of TPM3P9." (PMID 39865075, 2025). "The results of Co-IP and western blot analysis of tumor samples from the in vivo model confirmed the interaction between TPM3P9 and RBM4, and showed that TPM3P9 upregulated the expression of TCF7L2-L, an effect that was abolished by RBM4 overexpression." (PMID 39865075, 2025).
TPM3P9 also shares sentences with these, for which no sentence is quoted: colorectal cancer (1 paper); lung carcinoma (1).